CYP2E1 (cytochrome P450 family 2 subfamily E member 1)
Diseases named in the same sentence as CYP2E1 in open-access papers (continued):
Sharing a sentence is not in itself a finding about the gene and the disease.
lupus erythematosus (1 paper, 2018). An autoimmune, connective tissue chronic inflammatory disorder affecting the skin, joints, kidneys, lungs, heart, and the peripheral blood cells. "Multiple studies discovered that in patients of Chinese origin, single nucleotide polymorphism of CYP2E1 influenced the risk of lupus erythematosus and different cancers." (PMID 30131698, 2018).
malaria (1 paper, 2018). Malaria is a serious and sometimes fatal disease caused by a parasite that commonly infects a certain type of mosquito which feeds on humans. "Malaria can downregulate hepatic levels of cyp1a2, cyp2e1, and cyp3a11 mRNAs, causing prolongation of midazolam sleeping time and a slower clearance of chlorzoxazone." (PMID 30477109, 2018).
male infertility (1 paper, 2022). The inability of the male to effect fertilization of an ovum after a specified period of unprotected intercourse. "We therefore set out to evaluate the potential impact of HR-HPV genotypes in single infection (SI) and multiple infections (MI) that promote CYP2E1 expression, oxidative damage and pro-inflammatory cytokines, which can then contribute to sperm damage and male infertility." (PMID 35739948, 2022). "In this study, we explored the potential impact of high-risk (HR) HPV genotypes in single infection (SI) and multiple infections (MI) that promote CYP2E1 expression, oxidative damage and pro-inflammatory cytokines, possibly contributing to sperm damage and male infertility." (PMID 35739948, 2022).
metastatic tumors (1 paper, 2016). "Furthermore, we observed gain of CPT1C and CYP2E1 expression which may be indicative of increased mitochondrial β-oxidation and microsomal ω-oxidation, respectively, in metastatic tumors." (PMID 26725848, 2016).
methemoglobinemia (1 paper, 2025). An inherited or acquired condition characterized by abnormally increased levels of methemoglobin in the blood. "CYP2E1 is the primary isoenzyme responsible for this reaction in vivo, generating oxidative stress that predisposes susceptible individuals to methemoglobinemia." (PMID 41255504, 2025).
morbid obesity (1 paper, 2023). An excess of body weight, normally defined as an individual with a body mass index greater than 35 or a body weight greater than one hundred percent of ideal body weight. "Therefore, it has been proposed that CYP2E1 upregulation and CYP2E1-mediated oxidative damage play a major part in the mediation of steatohepatitis linked with morbid obesity." (PMID 36670991, 2023).
Neurodevelopmental delay (1 paper, 2025). "Polymorphisms in CYP3A4, CYP2C19, and CYP1A2 could impair detoxification of environmental toxicants, while dysfunction in CYP2E1 and CYP2D6 has been linked to oxidative stress and mitochondrial impairment—both implicated in neurodevelopmental delays." (PMID 40386062, 2025).
neuropathy (1 paper, 2018). A disorder affecting the nervous system that manifests with pain, tingling, numbness, and/or muscle weakness. "This delay in neuropathy progression of n-hexane treated groups might explained by the fact that 2,5-HD were generated from the metabolism in n-hexane treated models through CYP2E1." (PMID 30596762, 2018).
nonalcoholic fatty liver (1 paper, 2013). "In Cyp2e1 null-mice, increased expression of CYP4A has been observed during lipid accumulation in nonalcoholic fatty liver (NAFLD) and steatohepatitis (NASH) caused by high fat diets (HFD) or methione-choline-deficient diet." (PMID 24146933, 2013).
pancreatic cancer (1 paper, 2023). "For example, Nrf2-dependent microsomal glutathione S-transferase (MGST) expression was induced in CYP2E1-overexpressing HepG2 cells, and contributed to ferroptosis resistance in pancreatic cancer cells by inhibiting ALOX5 activity." (PMID 36993697, 2023).
polycystic ovary syndrome (1 paper, 2025). A disorder that manifests as multiple cysts on the ovaries. "The C-1054T polymorphism (rs2031920) in the CYP2E1 promoter region has shown a significant association with the risk of polycystic ovary syndrome (PCOS) in Chinese Han women, suggesting its important role in metabolic and inflammatory disorders." (PMID 40832467, 2025).
polyneuropathy (1 paper, 2013). A disease or disorder affecting more than one nerve. "The formation of 2,5-HD from n-hexane involves several genes and an association between the CYP2E1 gene might increase the susceptibility to develop n-hexane induced polyneuropathy." (PMID 23898939, 2013).
primary hyperoxaluria type 1 (1 paper, 2019). A rare disorder of glyoxylate metabolism characterized by the accumulation of oxalate due to a deficiency of the peroxisomal hepatic enzyme L-alanine: glyoxylate aminotransferase (AGT). "By literature reviewing, among the five genes, four have been well documented in HCC, including: ALDOB, IGFBP3, CYP2E1 and TOP2A, while AGXT was mostly studies in primary hyperoxaluria type 1, there are little reports of AGXT in HCC." (PMID 31771612, 2019). "Among the five genes, four (ALDOB; CYP2E1; IGFBP3; TOP2A) were well documented HCC related genes, while AGXT was mostly studies in primary hyperoxaluria type 1, but had not been reported in HCC." (PMID 31771612, 2019).
renal cell carcinoma (1 paper, 2021). "In renal cell cancer, it has been reported that the impact of the CYP2E1 genotype is quite contrary." (PMID 33673718, 2021).
Renal insufficiency (1 paper, 2020). A reduction in the level of performance of the kidneys in areas of function comprising the concentration of urine, removal of wastes, the maintenance of electrolyte balance, homeostasis of blood pressure, and calcium metabolism. "Taken together, our results suggest that low expression of XDH, CYP2E1, and SULT1A1, combined with the absence of renal AhR, may explain the low level of renal insufficiency observed in AhR−/− mice in the adenine-induced CKD model." (PMID 32260098, 2020).
respiratory depression (1 paper, 2024). A decrease in ventilation secondary to impaired signals from the central nervous system. "Thus, the CYP2E1 inhibitor fomepizole is unlikely to mitigate the analgesic effects of AAP, and high-dose AAP with fomepizole rescue may be a potent analgesic cocktail that spares the toxicities of narcotics, such as constipation, respiratory depression and ultimately dependance." (PMID 40236464, 2024).
retinal degeneration (1 paper, 2020). Degeneration of the retina. "If alcohol consumption upregulates CYP2E1 in retinal tissues in the same way that it does in liver, it should be considered as a risk factor since it could aggravate retinal degeneration in those patients with high baseline oxidative stress levels due to their ocular pathology including AMD." (PMID 32825644, 2020).
retinal diseases (1 paper, 2020). "On the other hand, because antioxidants such as NAC and DAS are effective against CYP2E1-mediated deleterious effects, their possible role as adjuvant therapies in retinal diseases deserves further research." (PMID 32825644, 2020). "At high oxidative stress levels, the induction of CYP2E1 expression and activity not only by EtOH but also by ROS, would be activating cell death and RPE degeneration promoting the progression of retinal diseases." (PMID 32825644, 2020). "Although CYP2E1 would play a key role in the generation of ROS and also in the alteration of the angiogenesis and inflammatory proteome profile in RPE cells, further studies are needed to understand the role of CYP2E1 in retinal diseases and specifically in outer blood–retinal barrier dysfunction." (PMID 32825644, 2020).
rheumatoid arthritis (1 paper, 2021). A chronic, systemic autoimmune disorder characterized by inflammation in the synovial membranes and articular surfaces. "A previous study reports that in serum of patients with rheumatoid arthritis, the hypomethylated regions in DUSP22 (another name of JKAP) gene and CYP2E1 gene are correlated with more active and erosive disease condition." (PMID 33083958, 2021).
Sensory axonal neuropathy (1 paper, 2025). An axonal neuropathy of peripheral sensory nerves. "Enzyme Inhibition and Activation: Inhibition of AChE and activation of CYP2E1 result in sensory axonal neuropathy and increased mortality." (PMID 40332597, 2025).
sickle cell anemia (1 paper, 2018). "The evaluation of variant allele of CYP2E1 in sickle cell anemia patients also suggested an association with hematological changes." (PMID 30154939, 2018).
skin cancer (1 paper, 2023). "Regarding the biological rationale for the interaction of THMs with NMSC, it had been pointed out that several genes that convert DBPs into reactive intermediates (CYP2E1 and GSTT1) were expressed in the skin and had a role in hereditary skin cancer susceptibility." (PMID 37927885, 2023).
status epilepticus (1 paper, 2021). Status epilepticus is defined as a continuous seizure lasting more than 30 min, or two or more seizures without full recovery of consciousness between any of them. "Severe status epilepticus increased CYP2E1 protein level in the hippocampus of mice, which was localized and cell specific, and antiepileptics phenytoin further induced localized CYP2E1 protein level in brain." (PMID 33967789, 2021).
Stroke (1 paper, 2021). Sudden impairment of blood flow to a part of the brain due to occlusion or rupture of an artery to the brain. "Indeed, mice in which CYP2E1 was deleted had the best stroke outcome." (PMID 33466250, 2021).
triple-negative breast carcinoma (1 paper, 2023). An invasive breast carcinoma which is negative for expression of estrogen receptor (ER), progesterone receptor (PR), and human epidermal growth factor receptor 2 (HER2). "Our analysis of variants in four genomic regions harboring ethanol metabolism genes in a large consortium of U.S. Black women identified significant associations between rs79865122-C in CYP2E1 and odds of ER- and triple negative breast cancer." (PMID 37308906, 2023).
Zinc deficiency (1 paper, 2013). A deficiency of the essential metal Zinc; an essential cofactor for many enzymes. "Zinc deficiency alone increased hepatic protein levels of CYP2E1 and p47phox as well as cell death receptors, TNFR1 and CD95." (PMID 24155903, 2013).
cancer (79 papers, 2006 to 2026). A tumor composed of atypical neoplastic, often pleomorphic cells that invade other tissues. "CYP2E1 induction is linked to the development of chemically-mediated cancers, via ROS or procarcinogen activation." (PMID 36993697, 2023). "Under conditions of high ethanol concentrations, however, ethanol can be metabolized by CYP2E1, which generates ROS as a byproduct of the reaction, potentially causing damage to DNA and proteins that contribute to cancer progression." (PMID 35454872, 2022). "After intraperitoneal administration, DEN is metabolized by cytochrome P450 (CYP2E1) in the liver, yielding an active mutagenic metabolite that can directly bind to nucleic acids, resulting in DNA mutation and cancer formation." (PMID 34299510, 2021). "There seems to be an association between wild-type c1/c1 genotype carriers of CYP2E1*5B and the risk of cancers of the oral cavity, larynx, esophagus, liver, lung, and pharynx compared to the variant genotypes." (PMID 29342885, 2018). "We found decreased urinary cancer risk among subjects carrying CYP2E1 RsaI/PstI c1c2 + c2c2 genotype and c2 allele (OR = 0.73, 95% CI = 0.68–0.79 and OR = 0.79, 95% CI = 0.74–0.85, respectively), with 3,301 cases and 3,786 controls from 14 studies." (PMID 29156840, 2017). "Using gene expression profiles, we established a gene-signature (CAV1, CD36, MLXIPL, CPT1C, CYP2E1) that strongly associated with epithelial-mesenchymal program across multiple cancers." (PMID 26725848, 2016). "Of special interest is CYP2E1 whose polymorphisms are related to substantial interindividual variation in metabolizing carcinogens and cancer risks." (PMID 22957075, 2012). "Previous reports implicate CYP2E1 RsaI/PstI polymorphism as a possible risk factor for several cancers." (PMID 23139769, 2012). "We also observed a significant association between the CYP2E1 DraI polymorphism and cancer risk for homozygote in the overall comparisons." (PMID 20969746, 2010). "We found that the variant homozygote of the CYP2E1 PstI/RsaI polymorphism was significantly associated with cancer risk in the overall comparisons, compared with the wild homozygote." (PMID 20969746, 2010). "Likewise, in E‐47 cells as well as Huh‐7‐CYP2E1+ cells, 100 mM ethanol for 48 h increased FABP4 production in a CYP2E1‐dependent manner, a soluble protein implicated in cancer development and progression." (PMID 39823133, 2025). "Accordingly, they hypothesized that the A1/A1 VNTR genotype of CYP2E1 gene may have a protective role against drinking- and/or smoking related cancers, and that A4/A4 of CYP2E1-VNTR may be a high-risk genotype during the early stages of cancer." (PMID 36494682, 2022). "Since the polymorphisms in the CYP2E1 gene would influence protein expression and the enzyme activity of allozymes encoded by the variant sequences, it has been suggested to be an important risk factor for susceptibility to several cancers." (PMID 32821545, 2020). "Studying the modifying effect of SNPs in CYP2E1 on the association between acrylamide and cancer risk may thus contribute important information on the causality of the association." (PMID 29445914, 2019). "As for CYP2E1 Rsa I/Pst I polymorphism, the results have demonstrated the mutated allele c2 may have different effects in different cancer type." (PMID 29156840, 2017). "Using 3,301 cases and 3,786 controls from 14 studies, we showed reduced urinary cancer risk in patients having CYP2E1 RsaI/PstI c1c2 + c2c2 genotype (OR = 0.73, 95% CI = 0.68–0.79, P < 0.001), comparing with the subjects carrying wide-type homozygous c1c1 genotype." (PMID 29156840, 2017). "It has been assumed that polymorphisms of CYP2E1*5 and CYP2E1*6 may lead to a decreased activity in CYP2E1 enzyme, thus linked to a lower risk of cancer." (PMID 28074086, 2017). "Therefore, studying the modifying effect of SNPs in CYP2E1 on the association between acrylamide and cancer risk contributes important information on the causality of the association." (PMID 27713515, 2016).
cancer (continued). "Therefore, the effect of the interactions between CYP2E1 polymorphism and alcohol consumption on cancer risk should be noted." (PMID 23139769, 2012). "Functional CYP2E1 gene polymorphisms that alter the transcriptional activity of the gene and thus its substances such as N-nitrosamines would influence the susceptibility of cancers." (PMID 22957075, 2012). "Furthermore, epidemiologic studies have also indicated that the CYP2E1 PstI/RsaI polymorphism is associated with cancer progression and prognosis." (PMID 22957075, 2012). "CYP2E1 encodes a member of the cytochrome P450 superfamily of enzymes which play a central role in activating and detoxifying many carcinogens and endogenous compounds thought to be involved in the development of cancer." (PMID 20969746, 2010). "Consequently, higher CYP2E1 activity has been associated with higher rates of cancer progression." (PMID 36418904, 2022). "However, it remains unclear whether CYP2E1 PstI/RsaI polymorphism is associated with the differentiation of cancer." (PMID 22957075, 2012). "The increased expression of CYP3A4 and CYP2E1 further suggests improved metabolic activity and functional maturation, which contribute to reduced proliferation and migratory behavior of the cancer cells." (PMID 41244070, 2025). "CYP2E1, one of the most active isoforms of the CYP450 family, has been shown to produce intracellular ROS, which can be linked to cancer development and metastasis." (PMID 41011284, 2025). "Conversely, some CYP450 enzymes, like CYP1A1, CYP1A2, CYP1B1, CYP2A6, and CYP2E1, have a role in the onset and development of many cancers by converting pro-carcinogenic substrates into carcinogens." (PMID 39062040, 2024). "High expression of cytochrome P450 family 2 subfamily E member 1 can protect COS-7 cancer cells against ferroptosis." (PMID 39711549, 2024). "CYP2E1 is a major catalyst for the oxidation of various small-molecule chemicals that are suspected to be cancer promoting, such as benzene, ethylene dichloride, trichloroethylene, and so on." (PMID 36766250, 2023). "CYP2E1 overexpression protected COS-7 cancer cells against ferroptosis, evidenced by an increase in the IC50 and a decrease in lipid ROS in WT versus Mock cells after exposure to class 2 inducers." (PMID 36993697, 2023). "Given the central role of CYP2E1 in inflammation and cancer progression, there is a strong rationale for the use of inhibitors of inflammation as therapeutic strategies for cancers." (PMID 37283464, 2023). "We found that both sham and cancer-bearing samples retained the zonated expression patterns of Alb and Cyp2e1." (PMID 36694005, 2023). "ARID1A was shown to enhance cancer initiation in part due to its transcriptional limitation of Cyp2e1, which resulted in increased reactive oxygen species (ROS) production." (PMID 35028302, 2022). "Phenethyl isothiocyanate is a potent cancer chemopreventive drug acting as an inactivator of some cytochrome P450s, including CYP2E1, which is involved in the bioactivation of carcinogens." (PMID 37861875, 2022). "Investigation of the association between cancer development risk and cytochrome P4502E1 (CYP2E1) gene polymorphism was significant." (PMID 35057823, 2022). "CYP1A1 and CYP2E1 are the important members of XME family and have been extensively studied as biomarkers for cancer risk prediction." (PMID 35996502, 2022). "The results of PPI demonstrated that the five TFs were tightly associated with many critical cancer related factors or pathways, such as SMAD4, MMP13, IL-5, IL-2, CYP2E1, CCNE1 and CDH1." (PMID 34405021, 2021). "This is firstly based on the fact that ROS produced in the process mediated by CYP2E1 is highly detected in several cancer cells." (PMID 33996531, 2021).